RNA5SP455 (RNA, 5S ribosomal pseudogene 455)
Synonyms: RN5S455
Gene: Ribosomal RNA pseudogene on chromosome 18 (44,071,583 to 44,071,701, forward strand). Ensembl gene ENSG00000202060.
Diseases named in the same sentence as RNA5SP455 in open-access papers:
RNA5SP455 is named in the same sentence as 1 disease in open-access papers, as found by Europe PMC text mining. Sharing a sentence is not in itself a finding about the gene and the disease. The quoted sentences say what the papers report.
Hypertension (1 paper, 2017). The presence of chronic increased pressure in the systemic arterial system. "Three detected genes were recognized by previous studies, and the other 5 loci/genes (MAN1A1, LMO3, NPAP1/SNRPN, DNAL4, and RNA5SP455/KRT8P5) were novel findings, which had no strong main effect on hypertension and could not be easily identified by single-locus genome-wide studies." (PMID 28642868, 2017).